BDNF (brain derived neurotrophic factor)
Diseases named in the same sentence as BDNF in open-access papers (continued):
Sharing a sentence is not in itself a finding about the gene and the disease.
Anxiety (continued). "The BDNF Val66Met polymorphism (rs6265) inhibits the activity-dependent release of BDNF and has been linked to reduced hippocampal volume and increased susceptibility to anxiety and depressive behaviors." (PMID 35875661, 2022). "However, our data demonstrated the opposite results where the lower CS levels were associated with higher BDNF mRNA expression levels in the hippocampus of low-anxiety rats." (PMID 36012411, 2022). "Minocycline treatment reduced locomotor deficits and anxiety-like behaviour associated with reduced phosphorylated tau protein levels, but it upregulated BDNF/CREB protein expressions in the mPFC in a comparable manner to memantine, with a higher dose of minocycline having better benefits." (PMID 36362262, 2022). "Specifically, the levels of Brain-Derived Neurotropic Factor (BDNF), a protein associated with changes in learning, memory, mood, and anxiety, have been found to increase in response to exercise due to increased production of the component molecules which make up the BDNF protein." (PMID 35055510, 2022). "It is reported that in a sample of sixty-four healthy participants, there are differential associations between the trait anxiety measure of harm avoidance (HA) and resting regional Cerebral Blood Flow (rCBF) in BDNF Val/Val and Met carriers in several regions relevant to stress regulation brain." (PMID 35815047, 2022). "We found that BDNF Val66Met genotype is associated with anxiety trait in PD patients." (PMID 35815047, 2022). "In this study, we examined the association between BDNF gene polymorphism and pathogenesis of panic disorder, and explored whether anxiety trait is associated with plasma BDNF level and BDNF Val66Met genotype in PD patients." (PMID 35815047, 2022). "We found that anxiety trait was associated with the BDNF polymorphism in PD patients." (PMID 35815047, 2022). "Hence, the deficiency of BDNF expression or the signaling pathway triggered by TrkB is linked to cognitive impairment and the development of anxiety‐like behavior." (PMID 35898162, 2022). "According to previous studies, FTO can affect neurogenesis, and the loss of FTO may lead to the change in the BDNF signaling pathway in the hippocampus, resulting in the increase in anxiety and the loss of working memory in mice." (PMID 35634463, 2022). "However, gut bacteria Klebsiella oxytoca and Escherichia coli cause anxiety with the suppression of BDNF expression in SPF mice." (PMID 34391441, 2021). "Indeed, EE exacerbated anxiety and social behaviors deficits in association with increased plasma BDNF level, larger volume of the hippocampus and infra-limbic region and higher number of neurons in the infra-limbic area (p < 0.05)." (PMID 33503967, 2021). "Adolescent female mice with the BDNF-Val66Met gene variant, which are characterized by deficient BDNF expression and increased anxiety-like behaviors, also showed an augmented probability of developing abnormal feeding behavior when subjected to caloric restriction and social isolation." (PMID 34600568, 2021). "A third possibility is that elevated BDNF is causing anxiety only in mothers with boys." (PMID 33462179, 2021). "Anxiety symptoms, or factors associated with anxiety, may drive changes in maternal BDNF that are only permissible in those mothers with a male fetus." (PMID 33462179, 2021). "The treatment of TSA promotes the BDNF and activity-regulated cytoskeleton-associated protein (Arc) gene expression in the amygdala of rats, increases the dendritic spine density, facilitates synaptic plasticity, and attenuates anxiety-like behaviors of rats." (PMID 33628222, 2021). "Reduction in BDNF levels is associated with anxiety‐like behavior." (PMID 34448534, 2021). "Also, uniquely associated with the anxiety/tension special factor was BDNF (brain-derived neurotrophic factor), which encodes a member of the nerve growth factor of proteins." (PMID 30867560, 2020).
Anxiety (continued). "We first used the Open Field test to investigate whether a reduction of cortical BDNF levels by ∼50% causes increased anxiety alongside elevated motor activity." (PMID 32651187, 2020). "In fibromyalgia syndrome cases, BDNF polymorphisms were associated with body mass index and anxiety score, specifically rs7124442 (A>G) (Fisher’s exact test χ2; p < 0.05; odds ratio (OR): 1.02) and rs2049046 (A>T) (Fisher’s exact test χ2; p < 0.05; OR: 0.55), respectively." (PMID 32859253, 2020). "Several studies support that the mechanisms underlying the complex manifestations of anxiety and depressive illness involve dysregulation of brain-derived neurotrophic factor (BDNF) and N-methyl-d-aspartate receptor (NMDAR), promoting disturbances in cellular signalling and neuronal plasticity." (PMID 32456135, 2020). "In this backdrop, we investigated if maternal separation causes coordinated long-term changes in stress response, anxiety-like behavior, basolateral amygdala structural plasticity, regulation of GR activation and regulation of BDNF within the basolateral amygdala." (PMID 32820184, 2020). "Furthermore, the Val66Met polymorphism of BDNF, which is associated with anxiety and depression, also impairs the dendritic targeting of Bdnf transcripts." (PMID 32460854, 2020). "In a rat model of posttraumatic stress with a single-prolonged stress through foot shock, grape powder administered at 15 g/L for 3 weeks following the stress protocol reduced anxiety-like behavior while preventing the loss of BDNF levels in the amygdala of affected animals." (PMID 31749681, 2019). "However, in another study, only in the hippocampus of GF female mice, BDNF levels increased and such enhancement was associated with decreased GluN2B levels and anxiety-like behavior." (PMID 30934533, 2019). "However, the epilepsy condition clearly shifts the relationship to the right of the graph, i.e., as compared to the control condition, a similar level of serum BDNF level is associated with a higher level of anxiety in pilo mice." (PMID 31331937, 2019). "In this study, we evaluated the occurrence of changes in BDNF and TrkB expression in two CNS regions, such as the hippocampus and prefrontal cortex, which are associated with development of altered behavioral patterns, stress responses and anxiety." (PMID 30794676, 2019). "Also, omega-3-fatty acid deficiency during pregnancy and lactation has been shown to alter BDNF-TrkB-signaling in the hypothalamus and cause anxiety-like behavior in the rat." (PMID 31572115, 2019). "In particular, certain BDNF SNPs and haplotypes were associated with anxiety symptoms." (PMID 30285822, 2018). "Since patients with FM have a significantly higher prevalence of anxiety disorders (13–63.8%), our findings imply that BDNF gene polymorphisms may indirectly affect FM through their effect on anxiety." (PMID 30285822, 2018). "Simultaneously, we conducted Western blot and immunohistochemistry analyses to explore potential mechanisms involving BDNF signaling that may underlie the anti-anxiety effects of ASH." (PMID 30602695, 2018). "Our results suggest that inflammation may cause anxiety-like behaviors by decreasing BDNF gene expression." (PMID 30460112, 2018). "A previous study revealed that the gut microbiome regulates microRNA expression in the amygdala, affecting factors such as miR-183-5p and miR-206-3p, both of which are implicated in influencing anxiety levels and the expression of neurotrophins such as brain-derived neurotrophic factor." (PMID 30344525, 2018). "However, data on the interactive effects of CM and genetic factors, such as the BDNF Val66Met polymorphism, on susceptibility to anxiety-related temperamental traits, such as AS, in adolescents is limited." (PMID 29805780, 2018). "Anxiety-like behavior associated with chronic colitis in mice was attenuated by B. longum administration, associated with decreased hippocampal brain-derived neurotrophic factor (BDNF) mRNA." (PMID 28601084, 2017).
Anxiety (continued). "Finally, we considered BDNF polymorphisms as an alternative genetic moderator, given its known role in neurodevelopment and a prior finding from this sample suggesting that BDNF moderated the association between prenatal anxiety and internalizing symptoms." (PMID 28614354, 2017). "In recent years, there has been a growing interest in the role of BDNF signaling in fear and anxiety regulation because associative synaptic learning occurring by fear or anxiety conditioning are thought to be a diathesis for the development of anxiety disorders." (PMID 28280960, 2017). "Furthermore, we demonstrate that this association in women is specific to Met allele carriers of BDNF rs6265, which is associated with impaired activity-dependent plasticity as well as multiple anxiety-related phenotypes including impoverished fear extinction." (PMID 28887539, 2017). "Similarly, AIE treatment with i.p injection of ethanol has been found to decrease adult hippocampal Ki67+ and DCX+IR while increasing HDAC activity and decreasing BDNF in association with increased anxiety." (PMID 28855864, 2017). "Moreover, BDNF rs6265 has been linked with anxiety-like phenotypes including fear extinction as well as clinical disorder." (PMID 28887539, 2017). "BDNF was only associated with the anxiety, attention and conduct scales when analyzed separately." (PMID 27489945, 2016). "Furthermore, a variant BDNF mouse model (BDNFMet/Met), with characteristics that are thought to reproduce the phenotype of humans with the Val66Met polymorphism, has increased anxiety-related behavior in the open field and elevated plus maze." (PMID 25932008, 2015). "In another study in which anxiety-related personality traits were correlated with BDNF polymorphism Val66Met, higher levels of trait anxiety were found in subjects bearing the Val/Val BDNF allele compared to Val/Met and Met/Met genotypes having reduced BDNF availability and secretion at synapses." (PMID 26539329, 2015). "A study reported a weak association between reduced serum BDNF and anxiety, but only in females." (PMID 26539329, 2015). "Interestingly, the Val66Met BDNF gene that plays a role in sensitivity to anxiety and cortisol stress response as well as baseline BDNF levels, is also implicated in motivation to exercise." (PMID 26779053, 2015). "Genetic evidence also points to similar temporal patterns of delayed fear extinction learning and increased risk for anxiety in both homozygote and heterozygote Met allele carriers of the brain-derived neurotrophic factor (BDNF) Val66Met genotype in mice and humans." (PMID 26161254, 2015). "KI mice that express BDNF containing a point mutation (valine 66 to methionine substitution, Val/Met 66) that mimics a mutation found in human populations, show impairment in BDNF secretion and exhibit high levels of anxiety-like behavior in open field and elevated plus maze tests." (PMID 24795586, 2014). "The BDNF gene polymorphism Val66Met has been found to be related to anxiety and mood disorders." (PMID 24596569, 2014). "Additional studies identified a subsequent step in the signaling cascade induced by BDNF-Arc signaling and synaptic plasticity contributes to both dysphoria associated with a genetic vulnerability for anxiety and to anxiety induced by environmental stressors, such as alcohol withdrawal." (PMID 23754976, 2013). "Our findings are supported by the recent study reporting that mice in which the Cdk5 phosphorylation sites are mutated into unphosphorylatable ones show increased BDNF transport and release associated with enhanced hippocampal neurogenesis and a decrease of anxiety-like behaviors." (PMID 24019939, 2013). "Changes in BDNF appear associated with increased anxiety behaviors." (PMID 23785661, 2013). "Since BDNF expression is stimulated by PACAP, and is decreased in PAC1 receptor-deficient mice, PACAP-stimulated BDNF expression may underlie the dorsolateral BNST cellular plasticity associated with anxiety and behavior disorders." (PMID 21524255, 2011).
Anxiety (continued). "Nevertheless, paradoxical patterns may also occur, as individuals with initially high BDNF (and better cognitive performance) could experience greater absolute winter decreases (“further to fall”), while anxiety-linked low BDNF levels may interact with seasonality in unpredictable ways." (PMID 41164095, 2025). "The downregulation of BDNF mRNA in these regions is associated with the manifestation of depressive-like behaviors and increased susceptibility to stress-induced mood disorders, including decreased social interaction, heightened behavioral despair, dysphoria, and elevated anxiety levels." (PMID 39203753, 2024). "Similarly, our results indicate that EMR may be associated with anxiety‐like behavior in mice, resulting in a significant downregulation of hippocampal BDNF expression, which is consistent with most reports." (PMID 37118929, 2023). "The authors also considered whether the reduced hippocampal iron in Cp-deficient mice may result in reduced levels of serotonin, norepinephrine, and decreased brain-derived neurotrophic factor (BDNF) expression, which may underlie the sensitive anxiety behavior in Cp-deficient mice." (PMID 38001850, 2023). "Specifically in humans, aerobic exercise was linked with the upregulation of serum levels of BDNF (a mediator of neurogenesis in the dentate gyrus) and with greater hippocampal volume and a subsequent decrease in psychological disorders (e.g., depression, anxiety)." (PMID 35159192, 2022). "Overall, our data support that serotonergic deficits within the corticolimbic nodes may represent an underlying mechanism of the anxiety-like phenotype; however, further studies are necessary to determine the exact region-specific role of BDNF in animal PD models." (PMID 36613906, 2022). "As suggested by previous research in animal models and humans, we hypothesized that (a) higher prenatal pandemic-related stress would be associated with increased methylation of the BDNF gene and (b) such an altered epigenetic status would associate with greater reports of anxiety after delivery." (PMID 35911240, 2022). "Furthermore, the nature–nurture interplay is viewed as possibly increasing the risk of developing excessive anxiety; for example, in the brain-derived neurotrophic factor gene (BDNFMet at codon 66) in interaction with early life, stress was found to predict neuroticism and higher anxiety." (PMID 34501748, 2021). "Furthermore, infants’ Val66Met BDNF genotype seems to affects also the association between antenatal maternal anxiety and infants’ genome methylation status at birth; a greater influence of maternal anxiety on the neonatal epigenome among Met/Met compared to Val/Val carriers was found." (PMID 34079501, 2021). "However, our results could observe some interesting findings in the FMS patient subgroups such as significant association of BMI and anxiety score with BDNF SNP at rs2049046 and rs7124442, respectively." (PMID 32859253, 2020). "Inflammatory mediators have been reported to reduce hippocampal BDNF levels, which may result in a decrease of hippocampal volume that, in turn, may be the principal cause of various mood disorders, including anxiety-like behavior." (PMID 31467638, 2019). "Possible association could imply potentially therapeutical usage of BDNF in anxiety." (PMID 31281833, 2019). "Consequently, we speculate the therapeutic function of NBP in chronic epileptic comorbidities associated with anxiety and depressive behavior by increasing the expression level of BDNF and Klotho." (PMID 30050437, 2018). "Similarly, enhanced amygdalar BDNF levels may cause anxiety, based on the findings that anxiety and amygdalar spinogenesis are enhanced in mice overexpressing BDNF58." (PMID 27305846, 2016).
Anxiety (continued). "However, the present study reports on a larger or similar sample (N = 97) than several previous studies that have found significant effects of genetic polymorphisms (the BDNF Val66Met and others) on the psychological or pharmacological treatment of anxiety and related disorders." (PMID 27355213, 2016). "Placing our data in the light of these previous studies, it is possible that increased BDNF promoter IV activity by the minor C allele of rs12273363 in the amygdala might increase these cellular processes with consequences for anxiety behavior and emotional memory." (PMID 22265241, 2012). "Moreover, it appears that abnormalities in BDNF signaling serve as predisposing factors to innate dysphoric states that may associated with alcohol-drinking behaviors, such as anxiety." (PMID 23584115, 2012). "For example,functional BDNF polymorphisms have been associated withanxiety-related personality traits, hippocampal volume in healthy volunteers, and episodic memory.Taken together, these data confirm the important role of BDNF inmemory, anxiety, and their interplay." (PMID 17502911, 2007). "Significant associations were found between the BDNF rs6265 polymorphism and pain catastrophising, OPRM1 rs1799971 and anxiety, and MAOA rs1137070 and depressive symptoms." (PMID 41460692, 2026). "Specific variants were associated with key psychological traits: BDNF rs6265 with pain catastrophising, OPRM1 rs1799971 with anxiety, and MAOA rs1137070 with depressive symptoms." (PMID 41460692, 2026). "Our data further revealed the IFN signaling pathway as a potential downstream effector of astrocytic BDNF in regulating anxiety." (PMID 40777598, 2025). "Specifically, we aim to investigate how age, sex, physical performance, body composition, cognitive function, and anxiety symptomatology influence both baseline BDNF levels and its change throughout the winter." (PMID 41164095, 2025). "Our findings show that both bacterial transplantation and FMT alleviated anxiety-like behavior and increased BDNF expression in the hippocampus." (PMID 40519780, 2025). "The BDNF-TrkB signaling pathway emerged as a key mediator, as pharmacological interventions of this pathway affected electrophysiological and anxiety-like behavioral changes." (PMID 40777598, 2025). "In this study, we reveal a pivotal role of astrocytic brain-derived neurotrophic factor (BDNF) in modulating anxiety sensitivity through coordinated regulation with hippocampal CA1 neurons." (PMID 40777598, 2025). "Astrocytic BDNF knockdown exacerbated synaptic dysfunction and heightened anxiety sensitivity, suggesting its essential role in neuronal responses to stress." (PMID 40777598, 2025). "Mice exposed to MeHg 0.5 mg/kg/day via drinking water from gestational day 7 until day 7 after delivery showed anxiety-like behavior and a decrease in brain-derived neurotrophic factor (BDNF) expression in 12-week-old male offspring." (PMID 40137494, 2025). "Using AAV-mediated astrocytic BDNF knockdown mice, we further demonstrated that astrocyte-derived BDNF is indispensable for regulating anxiety-like sensitivity through its impact on glutamatergic synaptic transmission." (PMID 40777598, 2025). "Combined with chemogenetic inhibition of CA1 pyramidal neurons, the knockdown manipulations exacerbated anxiety-like behaviors, emphasizing a synergistic effect between astrocytic BDNF signaling and neuronal activity in modulating stress response." (PMID 40777598, 2025). "Similar to Chai‐Hu‐Shu‐Gan‐San, XCHT was reported to attenuate depressive/anxiety‐like behaviors of social isolation‐reared mice by regulating the monoaminergic system, neurogenesis, and BDNF expression." (PMID 39981856, 2025). "Specifically, resistance training elevates BDNF levels, potentially preventing anxiety, mitigating age-related skeletal muscle degeneration, and improving muscle strength." (PMID 40373026, 2025).